TYR (tyrosinase)
Diseases named in the same sentence as TYR in open-access papers (continued):
Sharing a sentence is not in itself a finding about the gene and the disease.
Parkinson disease (49 papers, 2010 to 2025). A progressive degenerative disorder of the central nervous system characterized by loss of dopamine producing neurons in the substantia nigra and the presence of Lewy bodies in the substantia nigra and locus coeruleus. "Our study assessed seed oils’ in vitro neuroprotective potential from borage, calophyllum, and prickly pear, specifically targeting AChE, BChE, and tyrosinase, enzymes associated with Alzheimer’s and Parkinson’s disease." (PMID 40563295, 2025). "The extract exhibited significant in vitro enzyme inhibition activities, including anti-amylase and anti-glucosidase activities linked to diabetes and anti-cholinesterase and anti-tyrosinase activities associated with Alzheimer’s and Parkinson’s diseases." (PMID 40006842, 2025). "In particular, we evaluated the in vitro inhibitory activity of these oils against cholinesterase and tyrosinase, key enzymes implicated in the pathogenesis of Alzheimer’s and Parkinson’s diseases." (PMID 40563295, 2025). "The TYR enzyme catalyzes the conversion of L-tyrosine into dopamine and its excessive activity causes dopamine neurotoxicity associated with Parkinson’s disease." (PMID 39202972, 2024). "Tyrosinase is also involved in the synthesis of neuromelanin and the neuronal damage associated with Parkinson’s disease." (PMID 39458923, 2024). "The abnormal overexpression of tyrosinase it is known to cause a variety of pathological changes, such as pigmentation, light damage, and Parkinson’s disease, which are related to neurodegenerative diseases." (PMID 37627632, 2023). "In recent studies, tyrosinase has been considered to be implicated in neurodegenerative disorders like Parkinson’s disease." (PMID 33353058, 2020). "Second, both the up- and down-regulation of tyrosinase could cause the potential side effects, including complications like Parkinson’s disease." (PMID 40651969, 2025). "Moreover, the oxidative stress-related effects associated with tyrosinase are currently under investigation for their implications in neurodegenerative diseases, particularly in conditions such as Parkinson’s disease." (PMID 40693275, 2025). "The tyrosine-to-dopaquinone conversion catalyzed by tyrosinase may cause neurotoxicity, which has been connected to Parkinson’s disease." (PMID 35883492, 2022). "This suggests that tyrosinase might play a significant role in neuromelanin formation in the human brain and responsible for the neurodegeneration associated with Parkinson’s disease and Huntington’s disease." (PMID 28777326, 2017). "Tyrosinase is a key enzyme in the melanin synthesis in skin and hair, but it is also involved in the neuromelanin synthesis, which is used to identify susceptible neurons in Parkinson’s disease, and also generates dopamine-quinones, which are involved in oxidative stress." (PMID 36006126, 2022). "In the medical field, due to its action and similarity to mammalian tyrosinase, tyrosinase is used in the study of melanogenesis but also for the treatment of tumors and Parkinson’s disease." (PMID 41008174, 2025). "These important enzymes have been linked to a wide range of human diseases, including diabetes for α-amylase, Parkinson’s disease for tyrosinase, and Alzheimer’s disease for AChE and BChE." (PMID 41393958, 2025). "Tyrosinase exhibits a dual role in Parkinson’s disease, serving both as a catalyst for dopamine synthesis crucial for neurotransmission and as a catalyst for the conversion of dopamine to reactive oxygen species (ROS) and toxic metabolites." (PMID 39061039, 2024). "Tyrosinase is a copper-containing enzyme that plays a multifaceted role in the pathology of Parkinson’s disease (PD) through its involvement in oxidative stress, neuromelanin formation, and inflammatory responses." (PMID 39199238, 2024).
Parkinson disease (continued). "Tyrosinase (TYR) inhibition has become a recent target in Parkinson’s disease research, since TYR in excess amount (a copper-containing enzyme involved in the synthesis of melanin and neuromelanin formation) causes deterioration in functions of nigral neurons." (PMID 38338474, 2024). "The finding of new and reverse tyrosinase enzyme inhibitors, on the other hand, has enabled scientists to develop more accurate Parkinson’s disease prevention measures." (PMID 35883492, 2022). "Tyrosinase is an enzyme that generates melaninogenesis and is involved in cancer and Parkinson’s disease Yet, they found tyrosinase inhibition by structurally related flavonoids in tyrosinase." (PMID 35326885, 2022). "Bacterial tyrosinase has wide a spectrum of applications such as in the production of L-Dopa for Parkinson’s disease, melanin production, biocatalysis, bioengineering, phenol and dye removal, protein cross-linking, etc.." (PMID 36142889, 2022). "The inhibition of acetylcholinesterase enzyme is important for the treatment of Alzheimer’s disease, while tyrosinase inhibition is effective in Parkinson disease treatment." (PMID 33571277, 2021). "Tyrosinase is involved in neurodegenerative disorders, such as Parkinson’s disease, and in melanin-browning reactions important to the cosmetics and food industries." (PMID 34885832, 2021). "These enzymes which are key enzymes were intervening in some human pathologies such as diabetes for α-amylase, neurodegenerative disorders such as Parkinson’s disease for tyrosinase and Alzheimer’s disease for AChE and BChE." (PMID 34579487, 2021). "Dopaquinone and its derivatives produced via the biosynthesis of melanin by tyrosinase are thought to play a pivotal role in the degeneration of nigrostriatal dopaminergic neurons in Parkinson's disease." (PMID 26798334, 2015). "Taken together with previous studies showing dopamine synthesis and metabolism by tyrosinase, these results highlight therapeutic potential of intrastriatal autograft cell transplantation of melanocytes in patients with Parkinson’s disease." (PMID 23776585, 2013). "Inhibition of AChE and BChE may be helpful in the treatment of Alzheimer’s disease; similarly, Parkinson’s disease can also be fought by inhibiting the action of the tyrosinase enzyme." (PMID 38671929, 2024). "Tyrosinase also catalyzes the formation of neuromelanins, while the excessive conversion of dopamine from the oxidation of dopaquinones results in neuronal disorders which link tyrosinase with neurodegenerative diseases such as Parkinson’s disease." (PMID 36142889, 2022). "Furthermore, we investigated the inhibition of tyrosinase, an enzyme related to another neurodegenerative disease, Parkinson’s disease (PD)." (PMID 35009126, 2022). "Nevertheless, other enzymes may be potential targets for pesticides, such as other cholinesterases, e.g., butyrylcholinesterase (BChE), or tyrosinase, the latter is involved in dopamine metabolism and potentially involved in Parkinson’s disease." (PMID 36006126, 2022). "Therefore, tyrosinase inhibitors are becoming more and more valuable due to the huge markets of cosmetics, fruits preservation, and Parkinson disease prevention." (PMID 33473301, 2021). "Interestingly, a role of brain tyrosinase has been involved in age-dependent neuromelanin production in the pathogenesis of Parkinson’s disease, a neurodegenerative disease in which a neuroprotective role of Caff has been reported." (PMID 34199192, 2021). "Consistently, tyrosinase might also be a potential target for drug development for the treatment of Parkinson’s disease." (PMID 32486036, 2020). "Tyrosinase is a polyphenol oxidase enzyme involved in the synthesis of melanin (skin and hair) and neuromelanin, and it is considered a key target in the search for new drugs against Parkinson's disease." (PMID 30050651, 2018). "The inhibition of tyrosinase might prevent the aggravation of neurodegenerative disorders, such as Parkinson’s disease." (PMID 29463056, 2018).
Parkinson disease (continued). "Overexpression of tyrosinase leads to the massive oxidation of L-Dopa and dopamine into dopaquinone and dopamine quinone, both of which are found to result in neuronal damage and cell death, linking tyrosinase to neurodegenerative diseases, especially Parkinson’s disease (PD)." (PMID 29383286, 2018). "This links TYR to several neurodegenerative disorders such as Parkinson’s." (PMID 28777326, 2017). "Hence, the iron (II)-chelating activity of M. vulgare is of great significance, because it has been proposed as anti-tyrosinase activity, preventing the metal ions’ transition that can contribute to oxidative damage in neurodegenerative disorders like Alzheimer’s and Parkinson’s disease." (PMID 39458923, 2024). "Since tyrosinase is a rate-limiting enzyme in several undesirable melanogenesis processes, TS could also contribute to preventing fruit and vegetable browning, bacterial activity, cancer and Parkinson’s disease." (PMID 38592786, 2024). "Tyrosinase (TYR) converts L-tyrosine to l-DOPA (3,4-Dihydroxy-l-phenylalanine) and oxidizes L-DOPA to form dopachrome, inducing the production of melanin, a pigment that is associated with hyperpigmentation and neurodegenerative disorders, such as Parkinson’s disease." (PMID 36014295, 2022). "In addition, the toxicity of dopamine (produced by tyrosinase) could be intensified by overexpression of the enzyme, mainly found in patients with Parkinson’s disease." (PMID 33353058, 2020). "In addition, due to the expression of OTX2 in the central nervous tissue, and the presence of tyrosinase in the substantia nigra and other parts of the brain, the question of the role of OTX2 and the polymorphic site 3 in susceptibility to Parkinson disease arises." (PMID 22259223, 2012). "Furthermore, tyrosinase was also reported to catalyze the formation of dopamine quinone in human substantia nigra, which is a substance that may be involved in a dopamine neurotoxicity and various neurodegenerative diseases such as Parkinson’s disease." (PMID 32486036, 2020).
diabetes (42 papers, 2015 to 2026). "In parallel, molecular docking simulations were performed to examine the binding interactions of key compounds with α-amylase and tyrosinase—two enzymes implicated in conditions such as diabetes and skin pigmentation disorders." (PMID 39861165, 2025). "The investigation into the key enzymes in diabetes showed strong inhibition on α-amylase and α-glucosidase, whereas the skin-whitening properties are linked to inhibitory effects on tyrosinase." (PMID 38202342, 2023). "The inhibitory values for the blackthorn skin extract were significantly lower when compared to the positive control, suggesting a potential role in controlling a range of metabolic risk factors associated with diabetes and tyrosinase-induced pathological changes." (PMID 37627632, 2023). "Significant enzyme inhibition, particularly against tyrosinase and α-glucosidase, suggests potential applications in managing hyperpigmentation and diabetes." (PMID 42266350, 2026). "Overall, the methanol extract stands out for its strong antidiabetic potential, while all extracts exhibit some level of tyrosinase and urease inhibition, suggesting potential applications in managing diabetes, infections, and skin-related conditions." (PMID 39942760, 2025). "The enzyme inhibition assays further underscored the therapeutic potential of these extracts, with significant inhibitory effects on enzymes related to neurodegenerative diseases (AChE, BChE), diabetes (amylase, glucosidase) and skin pigmentation (tyrosinase)." (PMID 39765854, 2024). "Pharmacological properties reported for stilbenes include anti-lipidemic, anti-diabetes, hepatoprotective, anti-obesity, and anti-tyrosinase effects." (PMID 36771627, 2023). "Morus alba L. is used for a range of therapeutic purposes in Asian traditional medicine, and its extracts are reported to be effective against lipidemia, diabetes, and obesity, as well as being hepatoprotective and tyrosinase-inhibitory." (PMID 36771627, 2023). "Key clinical enzymes involved in neurodegenerative diseases AChE and BChE, diabetes (α-amylase and α-glucosidase) and skin whitening (tyrosinase) were also assayed." (PMID 36770677, 2023). "Considering complications related to diabetes, other clinical enzymes, namely, acetylcholinesterase (AChE), butyrylcholinesterase (BChE), tyrosinase, elastase and pancreatic lipase, were used." (PMID 35335362, 2022). "In this study, we evaluated the potential efficiency of this system for screening urine tyrosinase in different patient groups, including samples from patients with diabetes, chronic kidney disease (CKD), and those with both conditions." (PMID 31380262, 2019). "The potential inhibition of key enzymes of degenerative processes (cholinesterases, tyrosinase) and diabetes (amylase, glucosidase), the allelopathy toward Cichorium intybus, Dicondra repens, and Diplotaxis tenuifolia, and the in vivo toxicity on brine shrimp were also evaluated." (PMID 39856982, 2025). "The extracts exhibited strong inhibitory activity against acetylcholinesterase, butyrylcholinesterase, α-amylase, α-glucosidase, and tyrosinase, indicating potential therapeutic applications for global health issues such as skin hyperpigmentation, Alzheimer’s disease, and diabetes mellitus." (PMID 39410171, 2024). "In comparison to non-transformed shoots, transformed shoot lines exhibited a higher capability for the inhibition of enzymes related to neurodegeneration (acetylcholinesterase and tyrosinase), diabetes (α-amylase), and obesity (pancreatic lipase and cholesterol esterase)." (PMID 39202972, 2024). "Depsidones could have the potential as lead metabolites for neurodegenerative illnesses and diabetes through their inhibition of butyrylcholinesterase, tyrosinase, α-glucosidase, and acetylcholinesterase enzymes." (PMID 37197584, 2023).
diabetes (continued). "In addition, this work appraised the possible application of Lavandula coronopifolia Poir for the management of key enzymes of hyperpigmentation (tyrosinase), skin aging (elastase), diabetes (α-amylase), and neurodegenerative diseases." (PMID 35408473, 2022). "In conclusion, the crude extract and carpachromene exhibit significant urease, tyrosinase, and phosphodiesterase inhibitory activity which might be used against diabetes and bronchoconstriction." (PMID 36582600, 2022). "Lastly, the anti-enzymatic assays unveiled that the investigated spices exhibited a mild modulation of several key enzymes (cholinesterases, tyrosinase, glucosidase, and amylase) targeted in the management of chronic diseases, such as Alzheimer’s disease, type 2 diabetes mellitus, or skin disorders." (PMID 34961163, 2021). "In addition to their chemical composition, all extracts were also evaluated for three clinically important enzymes involved in common pathologies including skin problems (tyrosinase), diabetes (α-amylase), and inflammatory disorders (lipoxygenase)." (PMID 32245104, 2020). "In addition, the inhibitory potential of the extract against the key enzymes responsible for world-alarming diseases like neurodegenerative disorder (acetylcholinesterase (AChE) and butyrylcholinesterase (BChE)), diabetes (α-glucosidase and α-amylase), and skin problems (tyrosinase) were estimated." (PMID 33406643, 2021). "Moreover, our study did not account for the effects of medications that are used for diabetes, hypertension and cardiac ailments on aqueous TYR activity, which are unknown to us." (PMID 28712540, 2017). "The root extract demonstrated notable α-amylase (IC50 = 2.99 mg/mL) and tyrosinase (IC50 = 1.34 mg/mL) inhibitory activities, suggesting potential applications in diabetes and hyperpigmentation management." (PMID 39861165, 2025).
oculocutaneous albinism type 1 (37 papers, 2013 to 2026). "Oculocutaneous albinism type 1 is a genetic disorder caused by the disruption of tyrosinase activity in the melanogenesis pathway." (PMID 40568124, 2025). "Homozygous or compound heterozygous mutations of Tyrosinase (TYR) cause oculocutaneous albinism type 1A." (PMID 41002986, 2025). "Among these subtypes, the most severe is oculocutaneous albinism type 1 (OCA1), caused by perturbations in the tyrosinase (Tyr) enzyme encoded by the TYR gene." (PMID 37685839, 2023). "The inherited disorder oculocutaneous albinism type 1 (OCA1) is caused by mutations in the TYR gene encoding tyrosinase (Tyr), an enzyme essential to producing pigments throughout the human body." (PMID 37685839, 2023). "TYR is commonly known as the albino locus since the homozygous or compound heterozygous mutations of this gene result in oculocutaneous albinism type 1 (OCA1), an autosomal recessive genetic disorder characterized by hypopigmented hair, skin and eyes." (PMID 34238381, 2021). "While mutations in the tyrosinase are commonly associated with oculocutaneous albinism type 1, the amino acid exchange at position 291 was found to be associated with coat colour dilution in Cervus elaphus." (PMID 32041521, 2020). "The human equivalent disorder, oculocutaneous albinism type 1A, is caused by a mutation in TYR gene located on chromosome 11q14.2 encoding tyrosinase." (PMID 32797202, 2020). "While variants in tyrosinase are commonly associated with oculocutaneous albinism type 1, an amino acid exchange at position 291 in TYR was found to be associated with coat colour dilution in this population." (PMID 33213385, 2020). "The tyrosinase gene (TYR) encodes a key enzyme in melanogenesis and is responsible for oculocutaneous albinism type 1 (OCA1)." (PMID 30205563, 2018). "Mutations of tyrosinase gene family are related to depigmentation and developmental defects of the eye including oculocutaneous albinism type 1 (OCA1) and microphthalmia." (PMID 25097674, 2014). "Mutations in the tyrosinase gene cause oculocutaneous albinism Type 1 (OCA1), an autosomal recessive disorder characterized by reduced melanin pigment in the hair, skin and eyes." (PMID 24392141, 2014). "The deer mouse albino strain studied here is of the oculocutaneous albinism type 1, having a mutation in the tyrosinase gene." (PMID 24260509, 2013). "It has been suggested that mutations in tyrosine (TYR) and tyrosinase-related enzyme 1 (TYRP1) may cause human oculocutaneous albinism type 1 (OCA1) and type 3 (OCA3)." (PMID 37235424, 2023). "Although the strategy for targeting protein transport may be unsuitable for disorders characterized by the complete loss of Tyrosinase activity, such as oculocutaneous albinism type 1A (OCA1A), it might be effective for patients with OCA1B, who have partially retained Tyrosinase activity." (PMID 41516372, 2026). "TYR gene mutation inhibits the production of TYR, directly affects the production of melanin, and then causes oculocutaneous albinism type 1 (OCA1)." (PMID 39228912, 2024). "Oculocutaneous albinism type 1 (OCA1) is caused by pathogenic variants in the TYR (tyrosinase) gene which encodes the critical and rate-limiting enzyme in melanin synthesis." (PMID 35027574, 2022). "Mutations in the tyrosinase gene (TYR) cause oculocutaneous albinism type 1 (OCA1), an autosomal recessive disorder characterized by a lack of melanin biosynthesis or reduced melanin pigment in the hair, skin, and eyes." (PMID 34360537, 2021). "Oculocutaneous albinism type 1 (OCA1) is an autosomal recessive disorder caused by mutations in the tyrosinase gene." (PMID 33458560, 2020). "A lack or decreased activity of tyrosinase causes a disorder known as oculocutaneous albinism type 1 (OCA1), which affects the skin, hair, and eyes of individuals." (PMID 29870551, 2018).